SNAI1 (snail family transcriptional repressor 1)
Diseases named in the same sentence as SNAI1 in open-access papers (continued):
Sharing a sentence is not in itself a finding about the gene and the disease.
triple-negative breast carcinoma (21 papers, 2018 to 2025). An invasive breast carcinoma which is negative for expression of estrogen receptor (ER), progesterone receptor (PR), and human epidermal growth factor receptor 2 (HER2). "Thus, loss of SNAI1 in the context of triple-negative breast carcinoma cells promotes an intermediary luminal progenitor phenotype that gains differentiation plasticity based on the dual transcriptional action of FOXA1 and AR." (PMID 36171192, 2022). "EBF1 is a tumor-promoting TF in triple-negative breast cancer, whereas SNAI1/2 are master regulatory TFs for organogenesis and wound healing in normal tissue as well as for the epithelial–mesenchymal transition (EMT) in cancer cells." (PMID 37234983, 2023). "Further analysis identified DDR2 as the most upregulated receptor tyrosine kinase and a shared downstream effector of FOXQ1 and SNAI1 in triple-negative breast cancer (TNBC) cell lines." (PMID 36713812, 2022). "High SNAI1 expression characterizes metastatic triple-negative breast carcinomas, and its knockout by CRISPR/Cas9 uncovered an epithelio-mesenchymal phenotype accompanied by reduced signaling by the cytokine TGFβ." (PMID 36171192, 2022). "In this study, we show that SNAI2, a mediator of EMT highly expressed in triple-negative breast cancer, is upregulated in endocrine-resistant cells, whereas other EMT-associated transcription factors, such as SNAI1/3, TWIST1/2, ZEB1/2, FOXC2, and GSC, are unaltered." (PMID 29921289, 2018). "We found that SNAI1, a driver of epithelial-to-mesenchymal transition (EMT), upregulates CD73 in triple negative breast cancer cells." (PMID 36465484, 2022). "Additionally, CDH6 correlated with stem-cell-related transcription factors, including FOXM1, SNAI1, SOX9, and MCM2, in triple-negative breast cancer." (PMID 35938030, 2022).
pulmonary fibrosis (19 papers, 2013 to 2026). Chronic progressive interstitial lung disorder characterized by the replacement of the lung tissue by connective tissue, leading to progressive dyspnea, respiratory failure, or right heart failure. "Conversely, SETDB1 can oppose TGF-β–induced EMT by repressing SNAI1, as reported in breast epithelial cells and pulmonary fibrosis models." (PMID 41493679, 2026). "We next addressed how the expression of EMT-inducing transcription factors, Snai1, Snai2, Twist1, Twist2, Zeb1 and Zeb2, changed in the lungs from WT and Plaur-/- mice at Day 7, 14, 21 and 28 after bleomycin-induced pulmonary fibrosis." (PMID 36674896, 2023). "Susceptibility to CS-induced pulmonary fibrosis might be influenced by genetic variations in EMT-related genes, such as Snail Family Transcriptional Repressor 1 (SNAI1), Twist Family BHLH Transcription Factor 1 (TWIST1), and Zinc Finger E-Box Binding Homeobox 1 (ZEB1)." (PMID 37371940, 2023). "For further confirmation that vincamine can modulate EMT in BLM-induced pulmonary fibrosis in the present study, the expression of TWIST, Snai1, and Slug genes was measured in addition to the levels of fibronectin, N-cadherin, and collagen proteins." (PMID 37375218, 2023). "In the pseudostratified monocultures of the HBECs we observed the TGF-β1–induced EMT program described in lung fibrosis leading to the enhancement of the expression of mesenchymal genes as ACTA2, CDH2 and EMT-related transcription factors SNAI1 and SNAIL2." (PMID 33711932, 2021).
thyroid cancer (17 papers, 2014 to 2026). "TGF-β promotes EMT-like phenotypic changes in thyroid cancer cells, accompanied by upregulation of SNAI1 and EMT-related markers, which is enhanced by TSH." (PMID 40490818, 2025). "In conclusion, TGF-β promotes EMT-like phenotypic changes in thyroid cancer cells, accompanied by upregulation of SNAI1 and EMT-related markers, which is enhanced by TSH." (PMID 40490818, 2025). "Previous studies demonstrated the regulation of BRAFV600E on Snail in thyroid cancer cell lines and the correlation between SNAI1 mRNA expression and lymph node metastasis in PTC patients." (PMID 35651980, 2022). "miRNAs regulate key signaling pathways and target genes (e.g., SNAI1, PSMD10) to exert dual roles (cancer-promoting or cancer-suppressing) in thyroid cancer development." (PMID 40530008, 2025). "In thyroid cancer, ETV5 promoted the mesenchymal morphology of cancer cells by regulating the mRNA levels of twist family BHLH transcription factors 1 (TWIST1) and snail family transcriptional repressors 1 (SNAI1)." (PMID 36872348, 2023).
pancreatic ductal adenocarcinoma (16 papers, 2017 to 2025). An infiltrating adenocarcinoma that arises from the epithelial cells of the pancreas. "It has been shown that inhibition of the SNAI1 pathway by GATA6-AS1 is associated with tumor proliferation and lung metastasis in pancreatic ductal adenocarcinoma (PDAC)." (PMID 40515636, 2025). "For instance, exposing pancreatic ductal carcinoma cells to conditioned pancreatic fibroblast media was sufficient to confer resistance to gemcitabine, potentially due to up-regulation of snail family transcriptional repressor 1 (SNAIL) and miR-146a in the recipient cells." (PMID 30071693, 2018).
lymph node metastasis (14 papers, 2009 to 2025). "Inclusion of 2 additional cases displaying SNAI1-positivity >10% in lymph node metastases defined a poor-prognosis group with significantly shorter EFS (median 5 vs. 42 months, p = 0.0007) and DSS (median 9 vs. undefined, p = 0.0005)." (PMID 20181105, 2010). "Slug and Vimentin levels were significantly increased in patients with T-stage ≥ T3, while patients who had lymph node metastasis had significantly higher HAS-2, SNAI1, TWIST1, N-Cadh, Slug, and MMP-9." (PMID 40149256, 2025). "We analyzed the correlation between the expression of SNCG and Snai1 and clinical parameters of OSCC in the TCGA database and focused on the correlation between the expression of SNCG and Snai1 and lymph node metastasis, T stage, and clinical stage." (PMID 35434126, 2022). "Univariate analysis showed that clinical stage (HR = 2.8405), lymph node metastasis (HR = 6.0870), differentiation (HR = 3.4393), SNCG expression (HR = 4.1987), Snai1 expression (HR = 3.3610), and SNCG/Snai1 (HR = 3.0648) were risk factors of OS." (PMID 35434126, 2022). "Overall 5/25 (20%) lymph node metastases were SNAI1-positive, 20/25 (80%) had less than 5% SNAI1 expression and none of the metastases was entirely negative for SNAI1." (PMID 20181105, 2010).
squamous cell carcinoma (14 papers, 2003 to 2023). A carcinoma arising from squamous epithelial cells. "Downregulation of ΔNp63α, the predominant p63 isoform in squamous cell carcinoma, was recently shown to occur in response to SNAI1 and to increase SCC invasiveness." (PMID 20181105, 2010). "The role of SNAI2 downstream of Runx2 in BCa is reminiscent of the role of its homologue, SNAI1, in EMT and metastasis of breast, ovarian, colon, lung and squamous cell carcinomas." (PMID 22151997, 2011). "In this study we examined the expression of SNAI1, E-cadherin, FAK and p63 in a cohort of patients with squamous cell carcinoma of the oral cavity (OSCC) treated at a center of tertiary/quaternary care." (PMID 20181105, 2010). "Snail1 (SNAI1), a member of the slug/snail family of transcriptional repressors, is one of the several transcriptional factors that can suppress E-cadherin gene expression in squamous cell carcinoma and is a potent inducer of EMT." (PMID 22479362, 2012).
endometrial cancer (13 papers, 2012 to 2025). Primary or metastatic malignant neoplasm involving the endometrium (mucous membrane that lines the endometrial cavity). "Consistently, upregulation of EMT-associated genes like TWIST1 and SNAI1 was demonstrated in an endometrial cancer stem-like cell line and treatment with EMT-blocker salinomycin inhibited the tumorigenicity of these cells." (PMID 35328833, 2022). "An aldehyde dehydrogenase (ALDH)-1high cancer stem-like cell subpopulation isolated from other endometrial cancer cell lines also showed increased expression of EMT-associated genes like SNAI1 as well as pluripotency markers Sox2 and Nanog." (PMID 35328833, 2022). "Low dose metformin, at least in endometrial cancer cell lines, appears to reduce the expression of SNAI1, TWIST and ZEB1 and could, therefore, influence the metastatic process, although this has yet to be proven in primary endometrial cancer samples." (PMID 31083574, 2019). "SNAI1, SNAI2, TWIST, and ZEB EMT TFs have been reported to be involved in EMT in endometrial cancer cell lines." (PMID 36766756, 2023). "We showed significant abnormalities in the expression of cancer-promoting genes in tissues proximal to endometrial cancer, with higher expression of MYC, NR5A2, SNAI1, and TWIST1, in tumor-adjacent tissues than in tumors, which suggests field cancerization effect." (PMID 36140779, 2022). "Recently, for endometrial cancer similar observations have been described confirming promoter-binding sites for the Wnt/β-catenin inducing transcription factor LEF-1 and, interestingly, also for the EMT inducing transcription factors SNAI1 and SNAI2." (PMID 22295114, 2012).
myocardial infarction (13 papers, 2016 to 2025). Gross necrosis of the myocardium, as a result of interruption of the blood supply to the area, as in coronary thrombosis. "Following myocardial infarction, elevated lactate levels facilitate endothelial-mesenchymal transition via snail family transcriptional repressor 1 (Snail1) lactylation, leading to heightened cardiac fibrosis." (PMID 38993478, 2024). "The vital roles of Brd4 and its inhibitor JQ1 have been proven in the epigenetic regulation of p300 in various profibrotic genes, such as NOX4, snail family transcriptional repressor 1 (SNAI1), and CTGF in IPF and myocardial infarction (MI) induced cardiac fibrosis." (PMID 36864460, 2023).
esophageal squamous cell carcinoma (12 papers, 2019 to 2024). Esophageal squamous cell carcinoma (ESCC) is a type of esophageal carcinoma (EC) that can affect any part of the esophagus, but is usually located in the upper or middle third. "Ma reported miR-30c functions as a tumor suppressor via targeting SNAI1 in esophageal squamous cell carcinoma (ESCC)." (PMID 32201529, 2020).
liver fibrosis (11 papers, 2012 to 2024). "Thymoquinone, a black-seed-oil-derived compound, suppresses liver fibrosis by upregulating miR-30a-5p to inhibit its target, such as snail family transcriptional repressor 1 (SNAI1), suppressing EMT." (PMID 36612314, 2023). "Thymoquinone, a black-seed-oil-derived compound, suppresses liver fibrosis by upregulating miR-30a-5p to inhibit its target, such as snail family transcriptional repressor 1 (SNAI1), inhibiting EMT." (PMID 36612314, 2023). "Expression of the Snail family transcriptional repressor 1 (Snail) has been demonstrated in fibrotic liver cholangiocytes and hepatocytes and is a central transcription factor in HSC activation, demonstrating its essential role in regulating liver fibrosis." (PMID 38338338, 2024).
oral cancer (11 papers, 2003 to 2025). "In a previous study which investigated the expression of SNAI1 in oral cancer cells, SNAI1 was found to be up-regulated by the highly expressed transforming growth factor (TGF)-β in OSCC cells." (PMID 38671227, 2024). "Therefore, the miR-34a-5p/AXL axis promotes the proliferation, metastasis, and EMT of oral cancer cells through the AKT/glycogen synthase kinase (GSK)-3β (GSK-3β)/β-catenin/SNAI1 signaling cascade." (PMID 33917482, 2021). "Altogether, these results demonstrated that PGRMC1 was required for human oral cancer invasion and migration via regulating EMT‐inducing transcription factors SIP1, Snai1 and Twist." (PMID 32672400, 2020).
oral squamous cell carcinoma (11 papers, 2010 to 2025). "We hypothesized that SNAI1 reactivation occurs in oral squamous cell carcinoma (OSCC) where it might also be associated with focal adhesion kinase (FAK) expression and p63 loss." (PMID 20181105, 2010). "However, the association between SNCG and Snai1 and the effect of their combination on oral squamous cell carcinoma (OSCC) are unknown." (PMID 35434126, 2022). "Studies have shown that Clostridium nucleatum can promote the EMT in oral squamous cell carcinoma by regulating the lncRNA MIR4435-2HG\/miR-296-5p\/Akt2\/SNAI1 signaling pathway, thus enhancing cell migration." (PMID 36539710, 2022). "For instance, propofol may promote tumor metastasis through GABAA R-TRIM21-Src mechanism, and clinical concentrations of propofol promote migration and invasion by upregulating SNAI1 in oral squamous cell carcinoma." (PMID 37490168, 2023). "Consequently, the expression of the EMT transcription factor snail family transcriptional repressor 1 (SNAI1) is upregulated, promoting the EMT process in oral squamous cell carcinoma cells." (PMID 37998733, 2023).
esophageal cancer (10 papers, 2011 to 2025). A primary or metastatic malignant neoplasm involving the esophagus. "The transcription factor SNAI1, encoding Snail1, is important for metastatic progression in esophageal cancer whereas the microRNA (miRNA)-203 has been shown to function as an inhibitor of metastasis in EC." (PMID 32760222, 2020). "In line with this, we found that STAT6 regulates SNAI1, another typical marker of EMT, which has an important role in E-cadherin expression and that the levels of SNAI1 were inversely related with E-cadherin expression, as reported in esophageal cancer." (PMID 32244885, 2020).
head and neck squamous cell carcinoma (10 papers, 2011 to 2022). A squamous cell carcinoma that arises from any of the following anatomic sites: lip and oral cavity, nasal cavity, paranasal sinuses, pharynx, larynx, and salivary glands. "The expression levels of MIR4435‐2HG and SNAI1 were found to be positively correlated in various carcinomas, including head and neck squamous cell carcinoma (HNSCC) in the online database TCGA‐Pan‐Cancer (ChIPBase v2.0)." (PMID 31997506, 2020). "Indeed, EZH2 did not regulate SNAI1 or SNAI2 gene expression in head and neck squamous cell carcinoma cell lines, and the inhibition of its expression repressed the expression of mesenchymal markers and inhibited migration and invasion capacities without modulating EMT-TF levels." (PMID 33291363, 2020).
invasive breast carcinoma (10 papers, 2009 to 2023). A carcinoma that infiltrates the breast parenchyma. "Another study demonstrated that the regulation of miR-204, -200c, -34a, and -10 plays a role in increasing the survival rate of invasive breast cancer by up-regulating SNAI1 and other genes." (PMID 36347335, 2023). "For SNAI1, amplification ranked first among all alteration types in colorectal adenocarcinoma (6.73%), esophageal adenocarcinoma (4.4%), and invasive breast carcinoma (3.41%)." (PMID 35898399, 2022). "Actually, simultaneous deregulation of miR200cand miR-30c could significantly reduce the survivalrate of breast invasive carcinoma cells via up-regulationof OCT4, SOX2, c-MYC, SNAI1, ZEB1, CDH2 and down-regulation of CDH1 (P=0.02)." (PMID 31376329, 2020). "Actually, deregulation of miR‐204, miR‐200c, miR‐34a, and miR‐10b simultaneously could significantly reduce the survival rate of breast invasive carcinoma via up‐regulation of OCT4, SOX2, KLF4, c‐MYC, NOTCH1, SNAI1, ZEB1, and CDH2 and down‐regulation of CDH1." (PMID 30710426, 2019).
metastatic tumors (10 papers, 2015 to 2025). "The shorter OS and/or PFS associated with the RNA expression of ZEB1 and SNAI1 by CTCs may indicate a more aggressive and potentially docetaxel resistant phenotype being present in the primary or metastatic tumour sites, which may promote disease progression in mHSPC patients." (PMID 36727071, 2022). "We found that the expression of TWIST1, SNAI1, ZEB1, hFN1, and MMP2 increased from healthy epithelial cells to primary and metastatic tumor cells, reaching the highest expression in mesenchymal cell models." (PMID 40332096, 2025). "Human-specific gene expression of SNAI1, GSC, FOXC2, KRT19, and STAM2, presumably originating from DTCs, was detected in the BM of all xenograft mice that also developed metastatic tumors." (PMID 29291741, 2018). "Our results also provided evidence that acetate promotes SNAI1 expression through ACSS2-mediated histone acetylation, implying that inhibition of ACSS2 may be an important strategy in the treatment of metastatic tumors." (PMID 32458971, 2020).
nasopharyngeal carcinoma (10 papers, 2011 to 2025). A carcinoma arising from the nasopharyngeal epithelium. "However, in a recent study of nasopharyngeal carcinoma SNAI1 expression associated with repressed E-cadherin expression while TWIST expression had no affect on expression of E-cadherin." (PMID 21834956, 2011). "BMAL1 inhibited epithelial-mesenchymal transition through the TGF-β1/SMADs/Snail Family Transcriptional Repressor 1 (SNAIL1) axis, thereby enhancing the radio-sensitivity of nasopharyngeal carcinoma." (PMID 40271211, 2025).
sarcoma (10 papers, 2014 to 2022). A usually aggressive malignant neoplasm of the soft tissue or bone. "RMS is the most common sarcoma in children and its development has been previously associated with SNAI1 transcription factor activity." (PMID 32354171, 2020). "Indeed, SNAI1 expression is associated with worse overall survival in sarcomas." (PMID 28556516, 2017).
diabetic nephropathy (9 papers, 2014 to 2025). "We recently reported that AGEs reduce EZH2 expression in podocytes, lowering the repressive mark H3K27me3 and inducing the expression of Snai1, p27Kip1, and Tgf-β, thereby promoting podocytes damage and diabetic nephropathy." (PMID 41227374, 2025). "qRT-PCR analysis revealed upregulation of genes known to contribute to diabetic nephropathy and kidney injury as Ctgf, Snai1, and p27Kip1." (PMID 41227374, 2025). "To examine whether AGE-BSA treatment alters the expression of known genes associated with proximal tubular cell damage in diabetic kidney disease and EMT progression, we measured mRNA levels of connective tissue growth factor (Ctgf), p27Kip1, and Snai1 genes in TKPTS cells." (PMID 41227374, 2025).
head and neck cancer (9 papers, 2014 to 2025). A primary or metastatic malignant neoplasm affecting the head and neck. "In head and neck cancer cell lines cultivated in a 3D matrix environment, the EMT status affected the cell morphology, stiffness, and invasiveness, and the knockdown of the EMT transcription factors (EMT-TFs) TWIST1 and SNAI1 was sufficient to modulate the intrinsic stiffness of these cancer cells." (PMID 38398085, 2024).
malignant glioma (8 papers, 2014 to 2025). A grade III or grade IV glioma arising from the central nervous system. "In tumor cells, layilin promotes malignant glioma invasion through snail family transcriptional repressor 1 (SNAI1), which suppresses nuclear metastasis associated 1 family member 3 (MTA3), while also inhibiting low-density lipoprotein (LDL) uptake." (PMID 41404063, 2025). "It was recently reported that the transcriptional repressors of the snail family, SNAI1 and SNAI2, play a role in the acquisition and increase of invasiveness in malignant gliomas." (PMID 40679044, 2025). "EMT, as a key factor of malignant glioma invasion enhancement, can be characterized by an increase in the expression of biomarkers, such as CDH2, VIM, FN1, SNAI1, SNAI2, ACTA2, and so on." (PMID 34034744, 2021).
adenoma (7 papers, 2012 to 2025). A neoplasm arising from the epithelium. "In addition, MMP2, SNAI1, and VEGFA contributed to proliferation and invasion of adenomas." (PMID 33425722, 2020).
clear cell renal cell carcinoma (7 papers, 2015 to 2022). "We aimed to determine prognostic value of six key EMT markers (CDH1, CDH2, SNAI1, SNAI2, VIM, TWIST1) in clear cell renal cell carcinoma (ccRCC)." (PMID 31915310, 2020).
colorectal tumors (7 papers, 2009 to 2023). "SNAI1 exerts its essential role in colorectal tumor progression and metastasis by regulating EMT pathway." (PMID 37179119, 2023).